KLF4 (KLF transcription factor 4)
Diseases named in the same sentence as KLF4 in open-access papers (continued):
Sharing a sentence is not in itself a finding about the gene and the disease.
prostate carcinoma (continued). "We find that a Hi-Myc C57BL/6 prostate cancer line grows more slowly in syngeneic Klf4(f/f);Lys-Cre compared with Klf4(f/f) mice when inoculated subcutaneously, but grows equally rapidly in C/EBPβ(f/f);Lys-Cre and C/EBPβ(f/f) hosts." (PMID 29324844, 2018). "The downregulation of miR-32-5p in response to cisplatin treatment promoted KLF4 expression, which resulted in a increase in the chemosensitivity of prostate cancer." (PMID 30176890, 2018). "Analysis of tumor-infiltrating lymphocytes (TILs) demonstrated markedly increased activated CD8 T cell numbers, and CD8 T cell depletion obviated the inhibitory effect of myeloid Klf4 deletion on prostate cancer growth." (PMID 29324844, 2018). "To investigate the role of KLF4 in Chemotherapeutic insensitivity of prostate cancer, we first analysed the expression level of KLF4 under cisplatin (CDDP) treatment and found that KLF4 expression was increased in response to cisplatin." (PMID 30176890, 2018). "Consistently, our data showed that BIK was increased in response to cisplatin treatment and we found that KLF4 upregulated the expression of BIK in prostate cancer cells and promoted cisplatin-induced BIK expression." (PMID 30176890, 2018). "Here, we evaluate several mechanisms potentially leading to up- and/or down-regulation of IGF2 expression in prostate cancer and present a novel role of Kruppel-like factor 4 (KLF4) as a transcriptional regulator of IGF2 binding in IGF2-DMR0." (PMID 29017567, 2017). "Actually, loss of Klf4 has been observed in many types of human tumors, including acute myeloid leukemia, lymphoma, prostate cancer, bladder cancer and neuroblastoma, and restored Klf4 expression inhibited cell proliferation in these cancer cells." (PMID 29212199, 2017). "A recent study demonstrated that in prostate cancer cell lines PC3 and LNCaP, KLF4 is associated with the proliferative activity of cells via the KLF4-KRT6/13 pathway." (PMID 29017567, 2017). "Utilizing prostate cancer cell lines, we found in LNCaP that KLF4 binds to hypomethylated IGF2-DMR0 and co-localizes with H3K27me3 and H3K9me3." (PMID 29017567, 2017). "In conclusion, our analyses reveal a potent role of KLF4 transcription regulation on IGF2 in prostate cancer." (PMID 29017567, 2017). "Ectopic KLF4 expression in androgen-independent prostate cancer cells induced AR expression and decreased cell proliferation, invasion and bone metastasis." (PMID 27991915, 2016). "In prostate cancer, Krüppel-like factor 4 (KLF4) depletion occurs frequently, suggesting a role as suppressor tumor." (PMID 27991915, 2016). "This study highlights the role of the KLF4-AR axis in androgen deprivation and reveals pivotal mechanisms responsible for castration-resistant prostate cancer development." (PMID 27991915, 2016). "In clinical prostate cancer specimens, KLF4 levels were positively correlated with miR-1 and AR levels." (PMID 27991915, 2016). "We further showed that KLF4 increases miR-1 expression levels and sustains as a tumor suppressor of prostate cancer." (PMID 27991915, 2016). "First, we observed that KLF4 overexpression in AR-negative prostate cancer cell lines increased miR-1 expression." (PMID 27991915, 2016). "Na and colleagues have reported that lncRNA UCA1 regulates the proliferation in prostate cancer cells through regulation of kruppel-like factor 4 (KLF4) and keratin 6/13." (PMID 27608009, 2016). "KLF4-dependent suppression of stem cells by miR-7 expression has also been reported in prostate cancer." (PMID 26840086, 2016). "In concordance with the tumor-suppressive effect mediated by KLF4 activation, we demonstrated that AR-induced KLF4 expression negatively regulates the proliferation and metastatic abilities of prostate cancer cells." (PMID 27991915, 2016). "We then performed reporter assays in prostate cancer cell lines by using the wild-type pri-miR-1-2 stem-loop promoter, containing KLF4-REs driving RFP reporter expression." (PMID 27991915, 2016).
prostate carcinoma (continued). "In summary, the proliferation and metastatic abilities of prostate cancer cells are closely regulated by KLF4 expression, supporting its role as a tumor suppressor in prostate cancer." (PMID 27991915, 2016). "We next validated the relationship between AR, KLF4 and miR-1 expression in human prostate cancer tissues from the Taylor Prostate Cancer Dataset and The Cancer Genome Atlas." (PMID 27991915, 2016). "KLF4 inhibition through the transient transfection with siKLF4 in LNCaP or stable transfection with shKLF4 in 22Rv1 prostate cancer cells reduced endogenous miR-1 levels." (PMID 27991915, 2016). "RNA activation-mediated overexpression of KLF4 inhibited prostate cancer cell proliferation and altered the expression of several downstream cell-cycle-related genes." (PMID 26087183, 2015). "KLF4 and another epithelial determinant, FoxA1, are direct transcriptional inhibitors of Slug expression in mouse and human prostate cancer cells." (PMID 25879941, 2015). "In prostate cancer, HDACis can stimulate H3 methylation and upregulate Klf4 expression via Sp1 downregulation." (PMID 25341045, 2014). "In agreement with our finding, Liu recently reported the reciprocal regulation of KLF4 and SLUG in TGF-β initiated prostate cancer EMT and demonstrated that TGF-β induced loss of KLF4 was sufficient to initiate SLUG induction and EMT." (PMID 22937066, 2012). "Notably, in colorectal, breast, and prostate cancers, KLF4 exhibits remarkable context‐dependent and dual roles, acting as either a tumor promoter or suppressor depending on the intricate network of signaling pathways." (PMID 41532367, 2026). "KLF4 exhibits dual roles in cancer cells, acting as a tumor suppressor in gastric, lung, and pancreatic cancers while promoting oncogenesis in breast, colorectal, and prostate cancers." (PMID 41532367, 2026). "Conversely, downregulation of KLF4 enhanced the aggressiveness of prostate cancer." (PMID 37031197, 2023). "This seemingly opposite effect in prostate cancer may be related to the subcellular localization of KLF4, i.e., KLF4 was usually expressed in the cytoplasm of highly malignant prostate cancers." (PMID 37031197, 2023). "In addition, certain signaling pathways such as TGF-β promoted the growth, metastasis and invasion of prostate cancer by directly downregulating KLF4 expression." (PMID 37031197, 2023). "At last, our findings demonstrated that LINC00673 silencing could inhibit proliferation and drug resistance of prostate cancer cells via suppression of KLF4 gene promoter methylation." (PMID 31881124, 2020). "Therefore, the current study aims to investigate the underlying mechanism by which LINC00673 regulates the development of prostate cancer in regard with KLF4 involvement." (PMID 31881124, 2020). "In addition, RT‐qPCR was applied to detect the expression of LINC00673 and KLF4 in prostate cancer cells (PC3, LNCap and DU145), paclitaxel‐resistant cell line (DU145/pr) and normal prostate epithelial cell line (RWPE‐1)." (PMID 31881124, 2020). "More importantly, the current study verified that LINC00673 silencing could suppress the proliferation and drug resistance of prostate cancer cells by attenuating the methylation of the KLF4 gene promoter." (PMID 31881124, 2020). "KLF4 may therefore be employed to identify patients with indolent prostate cancer who have good prognosis." (PMID 33266506, 2020). "Furthermore, RT‐qPCR detected that the expression of LINC00673 was higher while that of KLF4 was lower in prostate cancer tissues when compared with adjacent normal tissues (both P < .05)." (PMID 31881124, 2020). "Moreover, LINC00673 silencing was demonstrated to reduce methylation of the KLF4 gene promoter to elevate the expression of KLF4, thus suppressing the proliferation and drug resistance of prostate cancer cells." (PMID 31881124, 2020).
prostate carcinoma (continued). "Taken together, these findings suggested that LINC00673 knockdown could repress prostate cancer cell proliferation by attenuating methylation of the KLF4 gene promoter." (PMID 31881124, 2020). "In summary, these findings solidified that LINC00673 could inhibit drug resistance in prostate cancer cells by reducing methylation of the KLF4 gene promoter." (PMID 31881124, 2020). "Findings concerning the role of KLF4 in prostate cancer are contradictory." (PMID 33266506, 2020). "In one study, KLF4 was detected primarily in the cytoplasm of non-tumor prostate tissues, and it was suggested that subcellular localization of KLF4 may be an important factor in prostate cancer." (PMID 33266506, 2020). "In prostate cancer, the expression level of KLF4 has been shown to be downregulated." (PMID 30176890, 2018). "Furthermore, treatment with the miR-32-5p inhibitor resulted in an increase in KLF4 expression and luciferase activity elevation in prostate cancer cells." (PMID 30176890, 2018). "Thus, our data revealed that KLF4 is an essential regulator in cisplatin-induced apoptosis, and the miR-32-5p-KLF4-BIK signalling axis plays an important role in prostate cancer chemosensitivity." (PMID 30176890, 2018). "Similarly, we found that KLF4 was induced by cisplatin and that elevated KLF4 promoted prostate cancer cell apoptosis via transcriptionally upregulating BIK expression." (PMID 30176890, 2018). "Overexpression of KLF4 inhibited prostate cancer cell growth and metastasis." (PMID 30176890, 2018). "Although KLF4 was found to be a tumour suppressor in prostate cancer, the effect of KLF4 on Chemotherapeutic insensitivity is still unknown." (PMID 30176890, 2018). "Our data showed that miR-32-5p inhibited KLF4 expression in prostate cancer cells." (PMID 30176890, 2018). "Similarly, we found that miR-32-5p enhanced the chemoresistance of prostate cancer and inhibited cisplatin-induced apoptosis via reducing KLF4-BIK signalling pathway activity." (PMID 30176890, 2018). "Recently, increasing evidence has indicated that KLF4 plays a key role in prostate cancer." (PMID 30176890, 2018). "In conclusion, our findings implicate myeloid Klf4 in prostate cancer progression." (PMID 29324844, 2018). "Through combined RNA sequencing analysis and web-based miRNA resources, we found miR-32-5p was downregulated under cisplatin treatment in prostate cancer cells and was a candidate miRNA that might regulate KLF4 expression." (PMID 30176890, 2018). "However, an earlier study in prostate cancer cell lines, where a RNA- and vector-mediated KLF4 over-expression was achieved, suggested that KLF4 can also act in a tumor suppressive manner." (PMID 29017567, 2017). "In prostate cancer, where the miR-182 cluster also is highly expressed, indicative of poor prognosis and drives proliferation and invasion, KLF4 has been reported to contribute to the progression and have a key role on migration and proliferation of prostate cancer cells in vitro and in vivo." (PMID 28412746, 2017). "Despite the gaps in the understanding of KLF4 and its interplay with cell motility and proliferation pathways, we present a novel function for the KLF4-miR-1 axis—a new putative predictive and surveillance biomarker of antiandrogen therapy for advanced prostate cancer." (PMID 27991915, 2016). "Although KLF4 activity is repressed in several cancers and can have a tumor-suppressive effect, the specific role of KLF4 in AR pathway-activated prostate cancer remains unclear." (PMID 27991915, 2016). "Moreover, in prostate cancer cell lines, KLF4 binds to the miR-1 promoter and induces its expression." (PMID 27991915, 2016). "Taken together, these data suggest that KLF4 expression is upregulated by AR in prostate cancer." (PMID 27991915, 2016). "Restoration of KLF4 expression in vitro impaired migration and invasion of prostate cancer cells." (PMID 24429391, 2014).
prostate carcinoma (continued). "However, the cell cycle progression is also arrested as induced by KLF4 at the G2/M phase in the prostate cancer cell line." (PMID 23861801, 2013). "Interestingly, selenium induces KLF4 expression in two cancer cell lines, derived from either androgen-dependent or androgen-independent prostate cancer." (PMID 20119532, 2009). "Moreover, this leads to the premise that simultaneous downregulation of KLF4 with increased AR levels could indicate a less favorable prostate cancer prognosis." (PMID 33640491, 2021). "Taken together, our findings demonstrated that LINC00673 silencing could disrupt the methylation of the KLF4 gene promoter and consequently suppress cell proliferation and drug resistance in prostate cancer, illuminating potential for future therapeutic strategies for prostate cancer." (PMID 31881124, 2020). "However, the potential biological role of KLF4 in Chemotherapeutic insensitivity of prostate cancer is still unknown." (PMID 30176890, 2018). "To determine whether KLF4 can regulate AR expression, thereby creating a regulatory loop between AR and KLF4, we analyzed the consequences of modulating KLF4 expression on AR expression in prostate cancer cells." (PMID 27991915, 2016). "Therefore, prostate cancer samples with increased AR levels had increased KLF4 expression." (PMID 27991915, 2016). "Our results may aid in understanding individual intervariability in drug responses to consequently improve drug therapies: by modulating KLF4 expression to repress cancer malignancy, an alternative target may be identified to improve the efficacy of current prostate cancer therapy modalities." (PMID 27991915, 2016). "Even within a single cancer type, such as breast, prostate cancer and CRC, KLF4 can exhibit opposing activities, acting as both a suppressor and promoter, a duality dictated by its expression level and the intricate TME." (PMID 41532367, 2026). "AZGP1P2 overexpression enhances the sensitivity of castration-resistant prostate cancer cells to docetaxel, reduces migration, increases apoptosis, and reduces prostate CSC markers, including KLF4 and SOX2, in castration-resistant prostate cancer cells." (PMID 41431719, 2026). "We find that MBNL1-AS1 has been reported to inhibit the progression of prostate cancer by sponging miR-181a-5p and regulating PTEN/PI3K/AKT/mTOR signaling and PTEN signaling happens to be regulated by PLK1, PAF, YB-1, TWIST, YY1, KLF4, and SALL4." (PMID 35518784, 2022). "Microarray‐based gene expression profiling of prostate cancer was employed to identify differentially expressed lncRNAs and genes, after which the expression of LINC00673 and KLF4 in prostate cancer tissues was determined using RT‐qPCR." (PMID 31881124, 2020). "KLF4 positively regulates the expression of miR-1, BCL2-interacting killer (BIK) and insulin-like growth factor 2 (IGF2) in prostate cancer." (PMID 33266506, 2020). "All these results verified that prostate cancer exhibits high expression of LINC00673 and low expression of KLF4." (PMID 31881124, 2020). "Our recent studies have indicated that KLF4 upregulates MGLL and BIK in HCC and prostate cancer cells." (PMID 30658712, 2019). "Utilizing prostate cancer cell lines LNCaP and DU145, we demonstrated that KLF4 binds to hypomethylated IGF2-DMR0 and affects IGF2 expression in dependence to prevailing post-translational histone modifications." (PMID 29017567, 2017). "To elucidate TLR9-mediated transcriptional regulation, we focused on two key prostate cancer stem cell-related genes: NKX3.1 and KLF-4." (PMID 26046794, 2015). "Several of the identified targets genes are known mediators of prostate cancer cell “stemness” and self-renewal, such as NKx3.1, BMI-1, and SOX-4; some are also embryonic stem cell (ESC) regulators, such as KLF4 and SOX2." (PMID 26046794, 2015). "Some of these genes have known functions in prostate cancer, such as FGFR1, BCL2, HOXC5, HOXA4, TWIST1, EZH2, KLF4, CTGF." (PMID 19262738, 2009).
prostate carcinoma (continued). "Thus, KLF4 may also play a key role in prostate cancer control." (PMID 20119532, 2009). "KLF4 contributes to monocyte development, and prostate cancer growth is slowed in the absence of myeloid KLF4 expression." (PMID 33266506, 2020). "Taken together, our data suggest that KLF4 is an essential regulator in cisplatin-induced apoptosis, and the miR-32-5p-KLF4-BIK signalling axis plays an important role in cisplatin sensitivity of prostate cancer." (PMID 30176890, 2018). "Thus, our data revealed that KLF4 is an essential regulator in cisplatin-induced apoptosis, and the miR-32-5p-KLF4-BIK signalling axis plays an important role in prostate cancer chemoresistance." (PMID 30176890, 2018). "Interestingly, we found that KLF4 knockout (KO) strongly reduced apoptosis, as indicated by a PARP cleavage decrease and elevated cell viability in prostate cancer cells." (PMID 30176890, 2018). "For instance, KLF4 was significantly down-regulated in prostate cancer cell lines compared with nontumorigenic prostate cells." (PMID 26087183, 2015). "Limitations of our study include lack of evaluation in the orthotopic prostate environment, which can be challenging due to early ureteral obstruction and difficulty with monitoring tumor growth, and lack of evaluation of the effects of myeloid KLF4 deletion using additional prostate cancer models." (PMID 29324844, 2018). "Mechanistically, a lower level of miR-7 expression existed in prostate cancer cells than in non-tumorigenic prostate epithelial cells, resulting in an over-expression of miR-7, which suppressed the stemness and tumorigenesis properties of PCSCs by targeting the KLF4/PI3K/AKT/p21 pathways." (PMID 36969009, 2023). "In summary, LINC00673 silencing could drive demethylation of the KLF4 gene promoter and thus inhibit the proliferation and drug resistance of prostate cancer cells, suggesting that silencing of LINC00673 and elevation of KLF4 could serve as tumour suppressors in prostate cancer." (PMID 31881124, 2020). "Our previous work identified LGALS3, KLF4, and non-canonical WNTs (i.e., WNT5A), as genes enriched in CTCs from overtly metastatic pancreatic, breast, and prostate cancer mouse models and patients." (PMID 32620742, 2020). "Similarly, miR-100 has a negative impact on prostate cancer cells by down-regulating the oncogene argonaute 2 (AGO2), which can mediate stemness factors of cancer cells such as OCT4, Krüppel-like factor 4 (KLF4), and c-myc." (PMID 36969009, 2023). "By comparing primary prostate cancer tissue samples grouped in TUR-BPH, RP-BPH and RP-PCa with regard to KLF4 expression, we could not detect obvious differences." (PMID 29017567, 2017).